CD4 (CD4 molecule)
Diseases named in the same sentence as CD4 in open-access papers (continued):
Sharing a sentence is not in itself a finding about the gene and the disease.
histoplasmosis (continued). "The CD4 + cell count was lower in the histoplasmosis group compared to the “no histoplasmosis” group (28 cells/μL, IQR 14–52 vs 73 cells/μL, IQR 30–137, P = 0.002)." (PMID 34384448, 2021). "When looking at the incidence in the <50 CD4 per mm3 strata, those having received fluconazole had a lower incidence of histoplasmosis than those who did not receive it (6.5 per 100 person-years vs 12.9 per 100 person-years, respectively)." (PMID 24498446, 2014). "Two cases of OI (one histoplasmosis and one TB ) occurred in patients without a CD4 + T-cell count." (PMID 38627642, 2024). "Since a substantial proportion of cases of histoplasmosis are diagnosed the same year as the HIV diagnosis, which entails rapid HAART initiation, one could question whether itraconazole primary prophylaxis still could add benefits since ARVs often allow a rapid increase in CD4 counts." (PMID 36730157, 2023). "For the 553 first episodes of disseminated histoplasmosis, median CD4 count was 171 (IQR 6–53) cells/mm3, and 89.9% of PWH were not on antiretroviral treatment when disseminated histoplasmosis occurred." (PMID 40562731, 2025). "The vast majority of HIV-infected individuals with histoplasmosis in INI were not receiving ART; a proportion had stopped HIV treatment (18.5%), and many were naïve to antiretroviral therapy (41.5%), and the median CD4+ was 70 cells/mm3, indicating severe immunological impairment." (PMID 37235319, 2023).
thymoma (66 papers, 2001 to 2026). A neoplasm arising from the epithelial cells of the thymus. "Type B3 thymomas and TCs were also associated with an increased frequency of CD4+ and CD8+ T cells expressing the inhibitory receptors PD1 and TIM3." (PMID 38629065, 2024). "Generally lower CD4+ counts are shown to be associated with higher incidences of ADCs and NADCs, but thymoma occurs when CD4+ counts are preserved." (PMID 34486210, 2021). "We noticed that previous report declared that MG is highly associated with the efficiency of thymomas to produce and export naive CD4+ T cells." (PMID 32985506, 2020). "Ströbel and coworkers demonstrated that paraneoplastic MG was highly associated with the capability of thymomas to produce and export naïve CD4+ T-cells." (PMID 29774108, 2018). "T-cell thymomas that develop in Pten-deficient mice are CD4+ CD8− mature T-cell thymomas." (PMID 37754262, 2023). "In a comparison of MG(+) and MG(-) thymomas, we could show that only thymomas capable of generating mature CD45RA+CD4+ T cells are associated with MG (p< 0.0001), while terminal thymopoiesis was abrogated in MG(-) thymomas." (PMID 14575152, 2003). "Consequently, as the activation of CD4+ T cells and inflammatory cytokines plays an important role in the development of thymoma-associated MG, XLOC_003810 lncRNA could contribute to the pathogenesis of these cellular pathways." (PMID 35529877, 2022). "This study presents a unique case of a patient with thymoma who experienced a decrease in CD4+ T lymphocytes following thymectomy and radiation therapy despite maintaining normal immunoglobulin levels." (PMID 39949750, 2025). "This study presents the case of a patient with thymoma who exhibited CD4 + T-cell immunodeficiency following thymectomy and radiation." (PMID 39949750, 2025). "Cortical thymomas resemble the thymic cortex in morphology and can produce polyclonal CD4+ and CD8+ thymocytes from bone marrow progenitors, which are then released into the bloodstream." (PMID 41008338, 2025). "The results showed that in the thymoma patients with AA, the inversion of the CD4+ T/CD8+ T lymphocyte ratio was consistently observed in tumor tissues (9/9), aligning with the findings in the serum." (PMID 40867301, 2025). "Before therapy, patients with MG showed a reduction in the frequency of chemokine receptor 3 (CXCR3)+ CD4+ T cells, especially in the thymoma group; however, CXCR3+ CD8+ T cells remained normal." (PMID 38378668, 2024). "T cells within thymomas can be found at different stages of maturation including DN and DP thymocytes and the more mature CD4 and CD8 SP populations." (PMID 38629065, 2024). "Conversely, type B3 thymomas and thymic carcinomas showcase a substantial infiltration of late-stage differentiated T cells, predominantly featuring either CD4 or CD8 single positivity, with a notable polarization towards a CD8 cytotoxic phenotype." (PMID 37849766, 2023). "Apart from one patient with thymoma (Patient #5), the T, CD4+ T, CD8+ T, and NK cell proportions in the other nine patients were mostly within the normal range or close to the normal range." (PMID 38444540, 2023). "In general, the TME of subtypes A, AB, B1, and B2 thymomas is infiltrated mainly by immature T-cells (CD4+ CD8+), which means that their immune status simulates the normal thymocytes." (PMID 36551568, 2022). "On the contrary, T-cells recruited to B3 thymomas and thymic carcinomas are dominated by terminally differentiated CD4-only- and CD8-only-expressing lymphocytes." (PMID 35887212, 2022). "Although previous studies have shown increased expression of OX40 on CD4+ T cells in thymomas from MG patients, little is known about the clinical significance and expression patterns of OX40 and OX40L in the peripheral blood of MG patients." (PMID 35265719, 2022). "In type A/B/B1 and B2 thymomas, immature T cells expressing both CD4 and CD8 are the most abundant type of cells." (PMID 36612283, 2022).
thymoma (continued). "The results suggested that the expression of OX40 on CD4+ T cells, MGFA classification, presence of thymoma, and AchR-Ab titers were significantly associated with relapse (P < 0.1)." (PMID 35265719, 2022). "In A/AB/B1/B2 thymomas, the majority of T-cell infiltration consists foremost of immature T-lymphocytes, with a double-positive (CD4+ CD8+) immunophenotypic profile, resembling that of normal thymocytes." (PMID 35887212, 2022). "PBK expression in KIRC, liver hepatocellular carcinoma, THCA, and thymoma was positively correlated with the infiltration of immune cells including B cells, CD4+T cells, CD8+ T cells, macrophages, monocytes, and neutrophils." (PMID 34859058, 2021). "Here we reported a case of acquired immunodeficiency with thymoma, with an unusual pattern of low CD4+ count with normal gammaglobulin levels." (PMID 31375083, 2019). "Here we report a case of acquired cellular immunodeficiency that was induced immediately after radiotherapy for thymoma, with an atypical pattern of low CD4+ count with normal gammaglobulin levels." (PMID 31375083, 2019). "More than 95 % of all thymomas (except for rare type A and B3) generate polyclonal CD4+ and CD8+ thymocytes from bone marrow progenitors." (PMID 26886206, 2016). "Our patient presented with a persistent low CD4+ T-cell count for 8 years following a combination of thymectomy and radiation therapy for thymoma." (PMID 25528459, 2014). "In this case report, we present a patient who developed a significant, sustained CD4+ lymphocytopenia and chronic idiopathic urticaria after a combination of thymectomy and radiation as treatment for thymoma." (PMID 25528459, 2014). "Lentiviral vectors expressing M-1 or M-4 isoform were transduced into the JM thymoma cells (CD4+, CD8α+, CD8β−) to generate stable cell lines that differed only in the expression of each CD8β isoform." (PMID 23533620, 2013). "Additionally, CD4+/CD8+ T-cell inversion in the serum was observed at a much higher rate in thymoma patients with AA [100.00% (9/9) vs. 24.44% (11/45), p < 0.001]." (PMID 40867301, 2025). "To further verify whether the inversion of the CD4+ T/CD8+ T lymphocyte ratio in serum is associated with thymoma, we performed a flow cytometric analysis to assess the CD4+ T/CD8+ T lymphocyte ratios in both thymoma and peritumoral tissues." (PMID 40867301, 2025). "Although the mechanisms underlying CD4+ T cell immunodeficiency in patients with thymoma are not well understood, reported cases consistently involve surgical intervention, thymectomy, and radiation." (PMID 39949750, 2025). "Therefore, CD4+ lineage maturation appeared to be impaired only in MG- thymomas suggesting a possible role of CD4+ T lymphocytes, together with a defective thymocyte selection, in favoring AD onset." (PMID 38629065, 2024). "Moreover, type B3 thymomas and TCs were characterized by an increased frequency of CD4+ Treg, distinguished by high CD25 expression of CD25." (PMID 38629065, 2024). "Notably, research has revealed a compelling finding in type B3 thymomas and thymic carcinomas with CD4 and CD8 single-positive T cell characteristics." (PMID 37849766, 2023). "Notably, in type A, AB, B1, and B2 thymomas, a higher prevalence of immature T lymphocytes displaying dual positivity for CD4 and CD8 immune markers is observed." (PMID 37849766, 2023). "In thymoma and PBMCs, we identified 13 specific clusters, which corresponded to cells in the process of differentiation, i.e., immature thymic CD4+ T cells to terminally differentiated effector memory CD4+ T cells (CD4 TEMRA)." (PMID 35869073, 2022). "In contrast, type B3 thymomas and thymic carcinomas are characterized by an immune cell infiltrate of terminally differentiated T cells expressing either CD4 or CD8, which may be more prone to mount an effective antitumoral response." (PMID 36612283, 2022).
thymoma (continued). "CD4+ T cells are activated, and inflammatory cytokines are significantly expressed in the thymic tissue of MG patients with thymoma.Positive correlation between XLOC_003810, which promotes the shift in Treg cells toward Th17 cells, and the clinical severity of the disease in MG-T patients." (PMID 35529877, 2022). "Hence, the increased populations of single-positive CD4 and CD8 T-cells, encountered in B2/B3 thymomas and thymic carcinomas, predispose to higher sensitivity to PD-L1 inhibition and render these TET subtypes more vulnerable to elimination by ICIs." (PMID 35887212, 2022). "Second, CD4+ T cells remained at a level much greater than 200/μl the time thymoma was diagnosed." (PMID 34486210, 2021). "We found that in all the cases reported, thymoma occurred when CD4+ counts were within a normal range, but the immune response in peripheral T‐cell repertoire remains unknown." (PMID 34486210, 2021). "Therefore, the impact of MDSC subpopulations on the GVT effect was determined by coinjecting the CD8+CD4− syngeneic thymoma cell line JM6 in BM-reconstituted mice." (PMID 34721430, 2021). "Indeed, MG+ thymomas of all major histotypes (except for type A thymomas) contain significantly more mature “pre-emigrant” CD4+ T cells than MG- thymomas." (PMID 32373124, 2020). "In addition, the number of CD4+ lymphocytes in the tumor tissue was significantly higher in type B1–3 thymomas than in the other types." (PMID 31683962, 2019). "However, no inversion of the CD4+ T/CD8+ T lymphocyte ratio was detected in peritumoral tissues (0/9), suggesting that the abnormal CD4+ T and CD8+ T lymphocyte ratios in serum may be associated with thymoma." (PMID 40867301, 2025). "Therefore, we hypothesize that abnormal CD8+ T lymphocytes produced by the thymoma can enhance the activity of CD4+ T lymphocytes, thereby promoting the production of autoantibodies and inducing the appearance of MG symptoms." (PMID 40867301, 2025). "Furthermore, analyses of MHC class II expression levels and the step-wise maturation of thymocytes inside different thymoma subtypes already gave strong hints that the mechanisms shaping the autoimmune CD4+ T cell repertoire are different in AB and B2 thymomas." (PMID 32373124, 2020). "The thymoma could promote intratumorous T-cell maturation to the CD4+ CD45RA+ naïve T cells." (PMID 25003519, 2014). "The paradox that the gain-of-function rs231775*A in predisposing to paraneoplastic MG could be explained by the nontolerogenic selection of CD4+ T-cells in MG-associated thymomas." (PMID 25003519, 2014). "The authors also reported that CD4+ and CD8+ T cells are more abundant in B2 and B3 thymomas and TC, compared to the remaining subtypes, paving the way for the possible use of ICIs as immunotherapy in TETs." (PMID 38629065, 2024). "They observed that both intratumor CD4+ and CD8+ T cells of type B3 thymomas and TCs showed higher anti-tumor activity, assessed as cytokine production upon PMA/ionomycin stimulation, compared with the other thymoma subtypes." (PMID 38629065, 2024). "Some flow cytometry results for CD4 and CD8 single-positive T cells in tumors have revealed that the same molecule was expressed in both B3 thymoma and thymic carcinoma." (PMID 36547157, 2022). "A cutoff value of 10% of double positive CD4+CD8+ thymocytes and small cell size (similar to that of a circulating lymphocyte) is strongly supportive of thymoma." (PMID 33969027, 2021). "The cluster analysis of T-cell profiles based on flow cytometric data revealed that type B3 thymoma and thymic carcinoma (B3/C) belonged to the hot cluster characterized by a high proportion of Tim-3+ and CD103+ in CD4 and CD8 single-positive T cells." (PMID 32132638, 2020). "In conclusion, the characteristics of CD4 and CD8 single-positive T cells in B3 thymoma and thymic carcinoma are favorable for anti-tumor immunity." (PMID 32132638, 2020).
thymoma (continued). "The abundance of both CD4+ lymphocytes and CD8+ lymphocytes in type B1–3 thymomas suggested that these lymphocytes surrounded the tumor cells and were ready to attack the tumor cells." (PMID 31683962, 2019). "Atm-induced AtmTgERT2-LBDAtm−/− mice were analyzed at 9 months of age for development of mature T cells, evaluating CD4 and CD8 markers, TCR-β expression and thymoma formation." (PMID 29472706, 2018). "The other 50% presented tumoral expression pattern of CD4 and CD8 markers and showed thymoma, although reduced in size." (PMID 29472706, 2018). "The presence of intratumor naive CD4+ T cells is a distinctive feature of TAMG, as naive CD4+ T cells are significantly reduced in thymomas without MG." (PMID 41008338, 2025). "Although most thymoma tissues from patients without AA also exhibited an inversion of the CD4+ T/CD8+ T lymphocyte ratio, it cannot be ruled out that abnormal T lymphocytes in the serum are associated with thymoma." (PMID 40867301, 2025). "Compared with HC, CD8+ but not CD4+ subsets among CD45RA+ T cells increased in the blood of patients with thymoma." (PMID 38378668, 2024). "On the contrary, in MG- thymomas, a decreased intratumor CD4+/CD8+ ratio within the naïve T cell compartment was observed suggesting that thymopoiesis in MG- thymomas is skewed toward CD8 rather than CD4 T lymphocyte commitment." (PMID 38629065, 2024). "Histology demonstrated bronchial mucosa with chronic inflammation composed predominately of CD3+ T lymphocytes (CD4+ > CD8+ T lymphocytes) and aggregates of CD20+ B lymphocytes, a pattern also observed upon review of the initial lung wedge resection diagnosing thymoma (images previously published)." (PMID 38954150, 2024). "In addition, we found that thymoma patients with higher SOX9 expression had less infiltration of B cells, CD4+ T cells, and CD8+ T cells, but higher infiltration of macrophages." (PMID 34778027, 2021). "Other report, on the contrary, stated that thymomas with MG exhibit higher level of naïve CD8+ T cells rather than naïve CD4+ T cells." (PMID 32985506, 2020). "Together, these findings suggest that CD4+ effector T cells that mature inside the abnormal microenvironment of thymomas and egress from them to the blood are critical to the development TAMG in thymopoietically active thymomas." (PMID 32373124, 2020). "Previous studies reported that MG+ thymomas contain a larger number of mature “pre-emigrant” CD4+ T cells than MG- thymomas and that most thymomas do not contain AIRE expressing cells irrespective of MG status." (PMID 32373124, 2020). "During immune cell population profiling according to tumor type, plasma cells and macrophages were more frequently observed in thymic carcinomas, whereas CD4+ and CD8+ T cells and dendritic cells were more frequently observed in the thymomas compared to the normal thymus." (PMID 31681591, 2019). "Such thymopoiesis plays a central role in the pathogenesis of TAMG: MG-positive but not MG-negative thymomas generate and export large numbers of mature CD4+ CD45RA+ cells to the blood." (PMID 26886206, 2016). "We do not know if he had immune defects as a result of the thymoma, or if he developed the severe CD4+ lymphocytopenia entirely secondary to thymectomy and/or radiation." (PMID 25528459, 2014). "Before treatment of the thymoma, his white cell and absolute lymphocyte counts were within normal limits; however, his CD4+ and CD8+ counts were not measured prior to surgery." (PMID 25528459, 2014). "Moreover, MG(-) thymomas were virtually depleted of regulatory (CD4+CD25+) T cells (regT), while regT were readily detectable in MG(+) thymomas, albeit at significantly reduced numbers compared to control thymuses." (PMID 14575152, 2003). "In addition, the inversion of the CD4+ T/CD8+ T cell ratio in the serum was significantly more frequent in thymoma patients with AA compared to those without AA (9/9 vs. 11/45, p < 0.001)." (PMID 40867301, 2025).
thymoma (continued). "The authors concluded that FC is a useful tool for discriminating mediastinal masses and that thymoma could be ruled out in all cases in which <10% of the small lymphocytes were CD4+CD8+." (PMID 33969027, 2021). "Further evaluation indicated almost-absent CD19 cells and low CD4 and CD8 counts, and coupled with his history of thymoma, this led to a diagnosis of Good syndrome." (PMID 40933428, 2025). "The percentage of CD4 + CD8 + cells in mediastinal masses is a leading criterium for FC differential between mediastinal lymphoma and thymoma in dogs, but the same is not valid in cats." (PMID 40822655, 2025). "Interestingly, after thymoma resection, the CD8+ but not CD4+ subset of CD45RA+ T cells in the blood decreased." (PMID 38378668, 2024). "In this study, we found that all thymoma patients with AA exhibited an inversion of the CD4+ T/CD8+ T lymphocyte ratio in their serum (i.e., a relative increase in CD8+ T lymphocytes in the serum), which was significantly higher than that observed in the thymoma patients without AA." (PMID 40867301, 2025).